NOPCHAP1 (NOP protein chaperone 1)
Description:
Client-loading PAQosome/R2TP complex cofactor that selects NOP58 to promote box C/D small nucleolar ribonucleoprotein (snoRNP) assembly. Acts as a bridge between NOP58 and the R2TP complex via RUVBL1:RUVBL2.
Synonyms: C12orf45; MGC40397; DDSR1
Tractability: PROTAC: ubiquitination databases record sites on it.
Gene: Protein-coding gene on chromosome 12 (104,986,316 to 105,074,197, forward strand). Ensembl gene ENSG00000151131.
Subcellular location: Nucleus
Subcellular location (Human Protein Atlas): Nucleoplasm; Nuclear membrane
Gene Ontology:
Molecular function: box C/D methylation guide snoRNP complex binding; protein binding
Biological process: box C/D snoRNP assembly
Cellular component: nucleus
Genetic constraint (gnomAD): Loss-of-function variants: 12 observed, 14.43 expected, observed/expected ratio (o/e) 0.83, 90% interval 0.53 to 1.35. The upper end of that interval is the gene's LOEUF score, 1.35, which puts it in group 5 of 6, group 1 being the genes least tolerant of losing a copy. Missense variants: 229 observed, 232.62 expected, observed/expected ratio (o/e) 0.98, 90% interval 0.88 to 1.1. Synonymous variants: 78 observed, 78.63 expected, observed/expected ratio (o/e) 0.99, 90% interval 0.82 to 1.2.
Homologues: Orthologues: macaque NOPCHAP1 (95% identical), chimpanzee NOPCHAP1 (94% identical), rabbit NOPCHAP1 (84% identical), dog NOPCHAP1 (78% identical), pig NOPCHAP1 (76% identical), rat Nopchap1 (73% identical), mouse Nopchap1 (71% identical).
Diseases named in the same sentence as NOPCHAP1 in open-access papers:
NOPCHAP1 is named in the same sentence as 2 diseases in open-access papers, as found by Europe PMC text mining. Sharing a sentence is not in itself a finding about the gene and the disease.
NOPCHAP1 shares sentences with these, for which no sentence is quoted: cancer (2 papers); ovarian carcinoma (1).